PLD3 (phospholipase D family member 3)
Diseases named in the same sentence as PLD3 in open-access papers (continued):
Sharing a sentence is not in itself a finding about the gene and the disease.
infection (5 papers, 2012 to 2025). The state of being infected such as from the introduction of a foreign agent such as serum, vaccine, antigenic substance or organism. "Considering the strain-specific proteins without a dependency on SLAMF1, Y strain infections displayed one common upregulated protein (RSAD2), and VFRA strain infections had one common downregulated protein (PLD3)." (PMID 39000601, 2024). "PLD3 was downregulated while PNLIP was elevated in Wolbachia mono-infected mosquitoes relative to other infection status." (PMID 32948809, 2020). "Numerous attempts to knock down PLD3 and directly examine its role in myogenic fusion were made using siRNA transfection and lentiviral shRNA infection." (PMID 22428023, 2012). "In addition, enzymes related to PA synthesis, including phospholipase D family member 3 (Pld3), Pld4, Dgki, Dgkk, and Dgkg, were upregulated after infection." (PMID 40463366, 2025). "Independently of SLAMF1, with the Y strain infection, there was one common upregulated protein, the radical S-adenosyl methionine domain containing 2 (RSAD2), and with the VFRA strain there was one common downregulated protein, the phospholipase D3 (PLD3)." (PMID 39000601, 2024).
neurodegenerative disease (4 papers, 2015 to 2024). A disorder of the central nervous system characterized by gradual and progressive loss of neural tissue and neurologic function. "Moreover, genes like PLD3, that has been linked to neurodegenerative diseases and studied in the context of neurons, is identified as monocyte-specific high regulatory load gene in our analysis." (PMID 26338775, 2015).
bacterial infections (1 paper, 2024). "RSAD2 is an IFN-stimulated protein that restricts various families of viruses, while PLD3 digests ssRNA and ssDNA in lysosomes/endosomes in viral and bacterial infections." (PMID 39000601, 2024).
inflammation (1 paper, 2024). Aberrant reaction of the microcirculation characterized by movement of fluid and leukocytes from the blood into extravascular tissues. "Pld4-deficient mice have inflammatory disease and an exaggerated TLR9 response, while Pld4- and Pld3-knockdown mice die before the age of 21 days due to lethal liver inflammation." (PMID 37979047, 2024).
kidney disease (1 paper, 2021). "Our studies indicated that homozygous mutation of PLD3 may result in a novel leukoencephalopathy syndrome with white matter lesions, hearing and vision loss, and kidney disease." (PMID 34267643, 2021).
PLD3 also shares sentences with these, for which no sentence is quoted: amyotrophic lateral sclerosis (3 papers); dementia (3); Ataxia (2); COVID-19 (2); Crohn disease (2); pancreatic cancer (2); autoimmune disorders (1); cerebellar ataxia (1); Cerebellar atrophy (1); cerebral atherosclerosis (1); glioblastoma (1); glomerulonephritis (1); IgA nephropathy (1); ischemic stroke (1); Lewy body dementia (1); liver cancer (1); mucolipidosis type IV (1); mucosal (1); multiple system atrophy (1); neurodevelopmental disorder (1); neurological disorders (1); neuronal ceroid lipofuscinosis (1); Obesity (1); Onset (1); pancreatic adenocarcinoma (1); paroxysmal non-kinesigenic dyskinesia (1); prion disease (1); rheumatoid arthritis (1); Splenomegaly (1); Stroke (1).
A further 3 diseases each share a sentence with PLD3 in 1 paper.